HGF (hepatocyte growth factor)
Diseases named in the same sentence as HGF in open-access papers (continued):
Sharing a sentence is not in itself a finding about the gene and the disease.
tumor (continued). "Most of the HGF in HNSCC is expressed by tumor-associated fibroblasts (TAFs) in the tumor microenvironment as an ineffective proenzyme that must be enzymatically degraded by the cell surface protease, matriptase." (PMID 37205904, 2023). "Hyperactive HGF/c-Met signaling in cancer represents a hallmark supporting tumor growth and survival, metastasis, cancer stemness, and chemoresistance." (PMID 37686233, 2023). "The protein HGF is primarily secreted by cancer‐associated fibroblasts (CAFs) and has a paracrine effect on nearby tumor cells." (PMID 38077251, 2023). "We analysed VEGF, due to the highly angiogenic nature of AML tumours, and HGF, due to its reported link to a cancer‐associated fibroblast state." (PMID 37337371, 2023). "HGF/Met signaling is associated with oncogenesis and tumor progression in different malignancies, and it induces aggressive cellular invasiveness, which is related to tumor metastasis." (PMID 37042307, 2023). "The growth factors produced by the tumor microenvironment, including hepatocyte growth factor (HGF) produced by tumor‐associated fibroblasts, critically affect the sensitivity to targeted drugs." (PMID 36416133, 2023). "CAF is involved in the matrix remodeling process and soluble factor secretion including VEGF, Exosomes, HGF, etc., which are the underlying mechanisms of tumor metastasis." (PMID 37908231, 2023). "While some tumor cells are capable of producing HGF and its splice variants, thereby modulating tumor progression through autocrine and paracrine signaling, stromal-derived HGF remains an indispensable element for the sustained activation of c-MET." (PMID 37919751, 2023). "Hepatocyte growth factor (HGF) has been shown to stimulate the proliferation, tube formation and migration of LECs through downstream ERK1 and PI3K signals, while the HGF/c-Met signal transduction axis is associated with tumor lymphangiogenesis." (PMID 37803421, 2023). "Studies have consistently shown that MET overexpression is a negative prognostic indicator in a variety of malignancies, and activation of the HGF-MET axis was associated with the drug resistance of tumor cells." (PMID 36142142, 2022). "HGF has been implicated in liver metastasis of several primary tumor types, and in this pre-metastatic setting, it promoted tumor cell proliferation, invasion, and migration." (PMID 35954395, 2022). "The interrupted VEGF-VEGFR2 signaling is substituted by cancer-associated fibroblasts and tumor cells through the secretion of HGF, EGF, and SDF-1α, by inducing the expression of their corresponding receptors and by direct cell to cell interactions." (PMID 35039644, 2022). "HGF in tumor microenvironment can be derived from both tumor cells and tumor associated stromal cells." (PMID 35978812, 2022). "Overexpression of HGF in HCC is associated with tumor invasion, metastasis, and the promotion of epithelial–mesenchymal transition." (PMID 35008398, 2022). "Hepatocyte growth factor (HGF), which is secreted predominantly by cancer-associated fibroblasts and present in the tumor microenvironment, promotes the survival and migration of cancer cells." (PMID 34975321, 2022). "The interruption of EGFR signaling by afatinib would lead to substitution by cancer-associated fibroblasts and tumor cells secreting HGF and SDF-1α14,16,17." (PMID 35039644, 2022). "In HCC, Wnt signaling has been reported to promote hepatocarcinogenesis, tumor growth and dissemination, while the hepatocyte growth factor (HGF) is also associated with increased hepatocarcinogenesis and metastasis." (PMID 36091074, 2022). "Recent studies have reported that HGF promotes the invasion of tumor cells associated with the up-regulation of MMP-2 and MMP-9." (PMID 36291760, 2022). "Given the large amount of preclinical data convincingly proving the causative role of HGF in drug resistance, targeting stromal HGF (or its tyrosine-kinase receptor MET expressed on tumor cells) is predicted to counteract tumor resistance." (PMID 36324182, 2022).
tumor (continued). "As an important regulator of many signaling pathways, the HGF/c-Met axis is closely associated with GC development and progression, tumor metastasis, and therapeutic response." (PMID 36209270, 2022). "In the majority of cancers, including HNSCC, MET is transcriptionally activated by stimuli such as hypoxia, inflammatory cytokines, stromal HGF, and pro-angiogenic factors, often abundantly present in the reactive tumor-associated stroma." (PMID 35326642, 2022). "Tumor specimens from patients with acquired drug resistance showed high expression of HGF in the context of MET amplification and the T790M mutation." (PMID 35840984, 2022). "It has been shown that lactate enhances the formation of HGF by tumor-associated fibroblasts, which in turn activates c-Met-dependent signaling pathways in cancer cells and confers resistance to c-Met inhibitors." (PMID 36551686, 2022). "In HNSCC, HGF is majorly secreted via tumor-associated fibroblasts (TAFs) in the tumor microenvironment." (PMID 35081970, 2022). "Lately, HGF/c-Met signaling was associated with drug resistance in tumor microenvironment via autocrine signaling." (PMID 36080304, 2022). "In vivo, we found that HGF was associated with increased tumor weights and sizes, while curcumin suppressed the HGF-induced increment in tumor weight and size." (PMID 34408780, 2021). "Our analysis was concordant with a number of clinical studies, showing that higher stage and tumor grade were associated with HGF-positive tumors." (PMID 34344422, 2021). "c-MET expression is prevalent at the invasive front of the tumor, where the neoplastic cells interact with HGF expressing cancer-associated fibroblasts and macrophages, inducing cell growth and survival, cell motility, and tumor metastasis." (PMID 33562604, 2021). "High levels of VEGF receptor (VEGFR), VEGF, c-MET, and the c-MET ligand hepatocyte growth factor (HGF) are associated with poor prognosis and tumor aggressiveness." (PMID 34180036, 2021). "While HGF/MET signaling has been traditionally implicated in tumor cell proliferation, survival, motility and epithelial-to-mesenchymal transition, recent data point at its pivotal role in controlling glucose metabolism in cancer cells." (PMID 34200749, 2021). "High tumor expression of c-Met and high basal serum levels of HGF, IL-6, CXCL11 and CXCL10 were significantly associated with reduced PFS and/or OS." (PMID 34200459, 2021). "The trend for higher cPSC counts to be associated with recurrent disease after tumour resection, and their modulation with HGF/c-Met inhibition suggests that these cells play a significant role in the metastatic process." (PMID 34199452, 2021). "HGF ligands comprise the fundamental pathway responsible for regulation of tissue repair after injury, and dysregulation of HGF signals have been implicated in both tumor growth and metastasis." (PMID 34185790, 2021). "LincRNA-associated ceRNA network plays a critical tumor-promoting role in CRC progression via regulation of HGF/c-Met signaling." (PMID 34050266, 2021). "HGF is the main mechanical link between pks+ (which encodes enzymes responsible for HGF synthesis) E. coli-induced senescence and tumor growth." (PMID 35069592, 2021). "We sought to understand associations between the HGF pathway and demographic characteristics, clinical features, and tumor subtypes within this racially diverse population." (PMID 34344422, 2021). "C-Met and its associated ligand—hepatocyte growth factor (HGF)—are often found in cancer patients with increased tumor aggressiveness and, consequently, poor prognoses." (PMID 33925941, 2021). "We were also unable to fully disentangle the role of basal-like subtype in driving HGF associations with tumor aggressiveness." (PMID 34344422, 2021). "High HGF expression was significantly associated with smaller tumor size (p = 0.006) and inferior TNM stage (p = 0.032)." (PMID 34970484, 2021).
tumor (continued). "In malignances, HGF is commonly synthesized and released by surrounded stromal cells, including cancer-associated fibroblasts (CAFs) and tumor-associated microphages (TAMs), triggering c-Met activation in a paracrine manner." (PMID 32626713, 2020). "Tumor-associated fibroblasts secrete HGF, whose overexpression activates downstream signals, causing primary or secondary tumor resistance." (PMID 32435640, 2020). "Tumour isoprostanes were positively associated with EGF in tumours and with HGF and NFκB activation in the gastrocnemius." (PMID 32472095, 2020). "In cancer cells, aberrant HGF/c-Met axis triggering, which is strongly linked to c-Met gene mutations and amplification, promotes tumor development/progression by inducing the PI3K/AKT, Ras/MAPK, JAK/STAT, SRC, Wnt/β-catenin, and other signaling pathways." (PMID 33226369, 2020). "Gene profiling of HGF stimulated monocytes showed an increase in transcription of genes associated with immunotolerance and tumor progression such as IDO, compared to monocytes stimulated by GM-CSF and IL-4." (PMID 32117721, 2020). "Loss of TPL2 in IMFs also resulted in the increased production of HGF and tumor susceptibility in TPL2-/- mice." (PMID 32724474, 2020). "The angiogenic factors HGF and follistatin were associated with poor prognosis in esophageal cancer patients when measured in the post-(chemo)therapeutic tumor tissue." (PMID 32023907, 2020). "In vivo M2 tumor-associated macrophages accumulate more in sorafenib-resistant tumors than in sorafenib-sensitive tumors and produce large amounts of HGF." (PMID 32532960, 2020). "Gene ARHGAP12 encodes a junctional complex protein that affects tumour cell adhesion, scattering, and migration driven by hepatocyte growth factor." (PMID 31212796, 2019). "Previous reports indicated that dysregulation of the HGF/c-MET pathway was found in multiple tumor types and was associated with unfavorable outcomes." (PMID 30782177, 2019). "In clinical applications, it was also observed that high methylation of the HGF promoter was associated with tumor progression and metastasis in NSCLC, indicating that HGF promoter methylation status can potentially act as a biomarker in NSCLC." (PMID 31602259, 2019). "Tumour-associated M2 macrophages were accumulated in sorafenib-resistance tumours more than in sorafenib-sensitive tumours in vivo and produced abundant HGF." (PMID 31130723, 2019). "HGF is secreted by tumor associated fibroblasts within TME as an inactive proenzyme, and once cleavage occurs it become a heterodimer that is capable of binding to c-Met." (PMID 29758011, 2018). "These activities were probably associated with overexpressed MMP-2 and HGF, as neutralization of these molecules markedly reduced tumor progression." (PMID 28956065, 2018). "Among the many bioactive molecules released by tumor and stromal cells, hepatocyte growth factor (HGF) is a crucial cytokine linked to promoting cancer progression." (PMID 30352967, 2018). "Our application of the EMT TF antibodies in xenograft experiments with the human HGF knock-in model illustrates the importance of examining multiple EMT-associated factors when characterizing tumor EMT phenotype." (PMID 29928062, 2018). "The c-Met, and its ligand HGF have been associated with tumor formation and progression to metastasis, with MET gene often overexpressed or mutated." (PMID 29455657, 2018). "As a growth factor, HGF promotes the growth and survival of cancer cells, increases tumor aggressiveness, stimulates metastasis and is associated with resistance to therapy." (PMID 30214428, 2018). "In HNSCC, the majority of HGF is secreted by tumor-associated fibroblasts (TAFs) in the tumor microenvironment as an inactive zymogen, requiring proteolytic cleavage by the membrane-bound protease matriptase." (PMID 28441771, 2017).
tumor (continued). "Accordingly, pharmacological inhibition of MET prevented the tumor-promoting activity of IKKβ-deficient fibroblasts, confirming the significance of HGF/MET signaling for the crosstalk between cancer cells and tumor-promoting fibroblasts." (PMID 28420162, 2017). "When human cancer cells are transplanted into immuno-deficient mice, the growth of the developing tumor (expressing human MET) cannot be fully sustained by micro-environment-derived HGF (secreted by mouse stroma cells)." (PMID 28445144, 2017). "The dysregulation of the HGF/c-Met signaling pathway has been implicated in the pathogenesis of cancer, such as tumor cell proliferation and survival, invasion, and metastasis." (PMID 29348891, 2017). "In tumor tissues, HGF is a key growth factor linked to increasing cancer progression and angiogenesis." (PMID 29276515, 2017). "Previous reports have identified associations between tumor and plasma HGF expression and clinical response to vemurafenib." (PMID 28147313, 2017). "A high sHGF value at later time-points of the treatment course would be associated with activity in the HGF/c-MET signaling pathway in the tumor." (PMID 29069748, 2017). "Accordingly, activation of the HGF/MET signaling pathway in tumor cells is associated with tumor aggressiveness and resistance to therapy, and predicts poor outcome in cancers patients." (PMID 28420162, 2017). "The binding of HGF to its receptor (c-Met, belonging to tyrosine kinase receptors) activates the signaling pathway that causes enhancement of angiogenesis in tumor tissues and prevents apoptosis, which all contribute to the outgrowth of tumors." (PMID 29276515, 2017). "MET, the receptor for hepatocyte growth factor (HGF), has been implicated in driving tumor proliferation and metastasis." (PMID 28406969, 2017). "MET-induced IL-1β triggers pro-HGF secretion in tumor-associated astrocytes, establishing a pro-metastatic inflammatory tumor microenvironment." (PMID 28420162, 2017). "Constitutive HGF/MET signaling in cancer cells is associated with increased tumor aggressiveness and predicts poor outcome in cancer patients." (PMID 28420162, 2017). "The HGF/c-Met signaling pathway is a pivotal component of tumor-associated angiogenesis that leads to tumor progression and metastasis via a sufficient supply of oxygen and nutrients through blood vessels." (PMID 28902178, 2017). "The receptor tyrosine kinase MET and its cognate ligand hepatocyte growth factor (HGF) have been implicated in diverse aspects of tumour pathobiology, including tumour growth, survival, neoangiogenesis, invasion, and dissemination." (PMID 28103611, 2017). "Accordingly, constitutive activation of the HGF/MET signaling pathway is associated with tumor aggressiveness, resistance to therapy and predicts poor outcome in many cancers patients." (PMID 27121052, 2016). "MET and its ligand hepatocyte growth factor (HGF) have been implicated in diverse aspects of tumor pathobiology, including tumor growth, survival, angiogenesis, invasion, and dissemination." (PMID 27714541, 2016). "As novel findings, our study indicated that serum level of HGF was associated with tumor shrinkage and time to progression of trastuzumab in HER2-positive patients with metastatic GC." (PMID 26716644, 2016). "HGF is secreted by cancer cells or by tumor-associated fibroblasts as pro-HGF, an inactive precursor." (PMID 27121052, 2016). "The increase in HGF level after partial hepatectomy results in rapid hepatocyte proliferation, and also causes the overexpression of H19 in the liver tissue and tumor, which explains rapid growth of liver metastases after partial liver resection." (PMID 26623562, 2016). "Matriptase is a tumor-associated type II transmembrane serine protease that is positively regulated during metastasis by activation of the latent forms of hepatocyte growth factor (HGF) and urokinase-type plasminogen activator (uPA)." (PMID 26539643, 2016).
tumor (continued). "Knockdown of MCT1 expression caused decreased hepatocyte growth factor (HGF)-induced as well as epidermal growth factor (EGF)-induced tumor cell scattering and wound healing." (PMID 27127175, 2016). "HGF is secreted by tumor cells or, more commonly, by tumor-associated fibroblasts as pro-HGF, the inactive precursor." (PMID 27121052, 2016). "MET receptor tyrosine kinase and its ligand hepatocyte growth factor (HGF) are implicated in tumor cell proliferation, invasion, and angiogenesis in NSCLC." (PMID 27200298, 2016). "Conversely, in a tumor prone background, HGF caused massive expansion of cycling satellite cells, triggering ERMS initiation." (PMID 26987019, 2016). "An important factor that contributes to liver regeneration and has been implicated in the context of resistance to targeted tumor therapy is hepatocyte growth factor (HGF)." (PMID 25905717, 2015). "Several prospective studies indicate that HGF secreted by fibroblasts reduces gefitinib sensitivity in tumor cells, but the underlying mechanism by which cancer cells survive, remains poorly understood." (PMID 25634113, 2015). "Previous studies have mainly focused on dysregulation of certain tumor-associated signaling pathways influenced by HGF." (PMID 26099202, 2015). "Hepatocyte Growth Factor (HGF) and Follistatin in the tumor tissue were associated with patient survival." (PMID 25885021, 2015). "HGF is a frequently detected ligand in the tumor stroma, mainly released by tumor-associated macrophages (TAMs) and by stromal fibroblasts." (PMID 25884419, 2015). "Overproduction of HGF by tumor cells or tumor-associated stromal cells and increased expression of the c-Met protein are two mechanisms that contribute to aberrant stimulation of this pathway." (PMID 26090722, 2015). "Using the median as cut-off, high HGF and Follistatin expression in the tumor tissue were associated with poor patients’ prognosis." (PMID 25885021, 2015). "In AEG tumor tissues alone HGF and Leptin were found to be associated with patients’ survival (p = 0.028 and p = 0.034)." (PMID 25885021, 2015). "The c-Met oncogene encodes the tyrosine kinase receptor for hepatocyte growth factor (HGF) and in tumor cells the constitutive activation of c-Met is associated with enhanced growth, invasion, and survival." (PMID 26189059, 2015). "In our study we reveal an Erk2 dependent crosstalk between tumor stroma associated HGF/Met signaling and tumor cell associated EGFR signaling." (PMID 25884419, 2015). "There are many cytokines secreted by aHSCs that are associated with tumor invasion and metastasis, including HGF, EGF, IL-1, IL-2, IL-6, MMP-2, MMP-9, TGF-β, TNF-α, VEGF and members of the Wnt signaling family." (PMID 26517671, 2015). "High HGF and Follistatin expression in the tumor tissue was associated with poor prognosis in all patients (p = 0.037 and p = 0.036)." (PMID 25885021, 2015). "Aberrancy in the HGF/MET pathway has been reported in multiple tumor types and is associated with tumor stage and prognosis." (PMID 28536405, 2015). "Hepatocyte growth factor (HGF) is another CAF-derived factor that has been implicated in promoting tumor progression and metastasis." (PMID 25011545, 2014). "Of note, peripheral edema is a frequently reported toxicity associated anti-HGF/MET antibodies across multiple tumor types and combination regimens." (PMID 24930887, 2014). "c-Met, a tyrosine kinase receptor for hepatocyte growth factor (HGF), is associated with metastasis and tumor invasion, decreased survival, and was recently investigated as a marker for CSCs in HNSCC." (PMID 24574924, 2014). "Metastasis-associated in colon cancer-1 (MACC1) is key in promoting tumor proliferation and invasion, and is mediated by the hepatocyte growth factor (HGF) and mesenchymal-epithelial transition factor." (PMID 25295116, 2014).